TNF (tumor necrosis factor)
Diseases named in the same sentence as TNF in open-access papers (continued):
Sharing a sentence is not in itself a finding about the gene and the disease.
tumor (continued). "Thus, a localized IR can elicit a systemic response that is mediated by cytokines and chemokines (TNF a, IL-1, IL-6, MCP-1, IL-8) and activate T cells directed against tumor-specific antigens, infiltrating both irradiated and non-irradiated tumor localizations." (PMID 37345088, 2023). "Taken together, our results suggest that Ce6-PDT has local antitumor activity, and its immune response, through the production of pro-inflammatory (Th1) cytokines such as TNF-α, IFN-γ, and IL-2, might restrict tumor growth on the non-irradiated right flank of the mice due to the abscopal effect." (PMID 36835310, 2023). "Several anti-cancer drugs also induce the secretion of TNF; auto- and paracrine TNFR signaling may not only synergize with apoptotic or necroptotic death, but also activate immunogenic NFκB signaling in tumor cells." (PMID 35625711, 2022). "While immunological tumor cell death with NCX4040 is not known at this time, our recent results using microarray analysis with low doses of NCX4040 indicate that NCX4040 significantly induces IL-6 gene and other immune responses genes (NFkB, TNF, etc.)in OVCAR-8 and NCI/ADR-RES cells." (PMID 35955744, 2022). "Also, to exclude the impacts of EL4 exosomes on the cytotoxicity of OT-I CTLs and the vitality of tumor cells, we tested the proliferation and cytotoxic cytokine production of OT-I cells, including IFN-γ, granzyme B, perforin, and TNF-α, and no significance changes were found." (PMID 34172932, 2021). "Moreover, the group of Tavernier have developed Activity-on-Target cytokines (so called Actakines) by fusing inactivated TNF or IFN-γ mutants to a CD13 antibody, leading to selective targeting to the tumor endothelium and complete tumor destruction without side-effects." (PMID 34576184, 2021). "Furthermore, tumour cells and non-malignant stromal cells secrete different growth factors such as TGF-β1, EGF, vascular endothelial growth factor (VEGF), FGF, TNF-α, IL-1β, and IL-6 that promote CAF trans-differentiation and activation, contributing to a pro-inflammatory profile and carcinogenesis." (PMID 34830058, 2021). "CD38 CAR-T cells secreted large amounts of TNF-α, IFN-γ, IL-2 and granzyme when incubated with CD38-positive tumor cells compared with pan-T cells, and there was no significant change in the killing effect of CD38 CAR-T cells on tumor cells that did not express CD38." (PMID 34513682, 2021). "Natural killer (NK) cells are a crucial component of the innate immune system, which can destroy tumor cells without previous sensitization, as well as the production of immunoregulatory cytokines early in an immune response, particularly interferon-γ (IFN-γ) and tumor necrosis factor-α (TNF)." (PMID 32973518, 2020). "We also examined whether IL1RN can be regulated by pro-inflammatory signals and found that TRAMP-C1 cell line treated with either LPS or TNFα did not affect IL1RN expression, supporting that the anti-inflammatory effects in tumor tissues are due to those recruited TILs, but not TRAMP-C1 cells." (PMID 32244522, 2020). "Thus, we further investigated the functional capacity of circulating and tumor‐infiltrating DCs to produce cytokines upon TLR triggering by performing intracellular labelling of IL‐12p40/p70, TNFα, IFNα and IFNλ1 within DC subsets stimulated or not with single or combined TLR‐Ls." (PMID 33282290, 2020). "In the present study, we found that the expression of IL-4, IL-6, TNF-α, and IFN-γ but not IL-10 dramatically increased after T cell interaction with peptides+HB100-108/pulsed DCs, indicating that this vaccine design has the ability to activate allogeneic T cells against tumor antigen." (PMID 32322595, 2020). "Despite the fact that TNFα and IL-1β induced potent p65 and JNK activation in T47D and MCF-7 luminal-A cells, CXCL8 levels were not increased but rather were decreased when the tumor cells interacted with MSCs in the presence of TNFα and IL-1β (Figures 6B1, 7B)." (PMID 31031757, 2019).
tumor (continued). "The expression of immune-modulating cytokines IL-6, TNFα and interferon gamma (IFNγ) was not significantly altered by the combination of cisplatin and P-MAPA, yet P-MAPA alone increased IFNγ expression in the OC tissues which can elicit anti-tumor immune responses by activation of innate immunity." (PMID 31443240, 2019). "Furthermore, whether in patients with MVI or without MVI, or in patients with maximum tumor size > 5 cm or ≤5 cm, high preoperative serum IL6, IL8, and TNF-α levels were distinctly correlated with shorter RFS." (PMID 31781194, 2019). "Indeed, as IDO can be activated by many stimuli such as IFN-γ and tumor necrosis factor (TNF)-α, IDO inhibitors may not work in a patient with a cold tumor, not infiltrated by T cells." (PMID 32039024, 2019). "The extracellular ligands belong to the tumor necrosis factor (TNF) superfamily, and TNF-related apoptosis inducing ligand (TRAIL) is a member of the TNF superfamily, which has been demonstrated to induce apoptosis in various types of tumor cells without toxicity to normal cells." (PMID 29444104, 2018). "However, TNFα and IL-6 levels did not increase in TLR4−/− tumor-bearing mice." (PMID 28536426, 2017). "Similarly, Vascular Endothelial Growth Factor (VEGF), a tumor-derived factor, tended (p = 0.061) to be increased in BCa patients; while other putative tumor-derived factors such as RANK-L, Hypoxia-inducible Factor 1 alpha (HIF1α) or TNF-α were not significantly altered." (PMID 29113405, 2017). "We then compared the effects of TNF blockade with either etanercept or infliximab on MCA 205 growth and found that both drugs efficiently and comparably inhibited tumor growth, indicating that anti-tumor effects were most likely due to TNF and not to sLTa neutralization." (PMID 27148266, 2016). "The results showed that TNF-α and IL-6 productions by monocytes incubated with NVD at different concentration levels (5000 and 2500 μg/mL) increased in vitro, but the proliferation activity of monocytes and tumor cell toxicity did not seem to be affected by NVD." (PMID 26339270, 2015). "Moreover, the expression levels were unaffected by PDT or RelA knockdown, altogether indicating that IL-10 and IL-12 did not modulate IL-6 and TNF-α signaling and did not play a role in the PDT response by tumor cells or the immunogenicity of PDT-afflicted EMT-6 cells in macrophages." (PMID 26307977, 2015). "Marked and dose-dependent increases of iNOS and TNF-α immunoreactivities were demonstrated in all platycodin D treated mice as compared with tumor-bearing mice, but gemcitabine 160 mg/kg did not influenced on the iNOS and TNF-α immunoreactivities in tumor masses." (PMID 25477992, 2014). "After priming with IFN-γ and/or TNF-α, the neutrophils from different sources could similarly induce the production of IFN-γ by the NK cells from naive mice, but not the NK cells from tumor-bearing mice and pG/pI6-mice." (PMID 25587026, 2014). "Another possible explanation for the lack of inhibition of TNF-α shedding in vivo is that shedding in trans could be occurring, where murine ADAM17 on host cells, which would not be regulated by D1(A12), could cleave TNF-α on adjacent human tumour cells." (PMID 22792380, 2012). "Indeed, we have established that these three inhibitors block the shedding of ADAM-17 targets such as TNFα, TGFα and amphiregulin (AREG) with the same efficacy (data not shown) whereas TMI-2 and TMI-005 only partially inhibit tumor cell growth and do not induce apoptosis." (PMID 23028451, 2012). "However, this increase could not participate in host defence against tumour cells by inducing apoptotic signals, as MDA-MB231 cells are resistant to TNF alpha." (PMID 12698185, 2003). "However, there are several factors that might potentially affect the process even in vitro culture of DCs with tumor necrosis factor (TNF) or GM‐CSF and CD40 ligand (CD40L) did not enhance the expression of costimulatory molecules, suggesting that tumor cells impair DCs' differentiation." (PMID 38351552, 2024).
tumor (continued). "Moreover, high concentrations of CKb11, TNF-α and IFN-γ were detected in tumors and ascites without significant changes in CKb11, TNF-α, IFN-γ levels in the serum, indicating locally activated anti-tumor immunity without obvious systemic inflammation responses." (PMID 38832303, 2024). "However, our study shows that TNF-α secretion is not altered in Nlrp6−/− macrophages, indicating that PmCQ2-induced TNF-α might not be involved in the development of tumorigenesis as this cytokine is tumor promoting." (PMID 36224650, 2022). "Hence, because of their unusual lack of response to TNFα, at this moment we are unclear if the effect of overexpressing BCA2 on NF-κB in MCF-12F cells is an accurate representation of the role of this E3 ubiquitin and SUMO ligase in the regulation of NF-κB in non-tumor breast tissue." (PMID 34589482, 2021). "Moreover, our results also indicate a significantly positive correlation among leptin, IL-6, TNF-α and HGF and TNM stage, and a significantly negative correlation between adiponectin and TNM stage; suggesting that it should be considered as an important factor in tumor growth." (PMID 29088874, 2017). "The cooperation we observed between SM-164/TNFα and doxorubicin further suggests that IAP antagonists may augment the efficacy of currently used chemotherapy regimens, and/or could permit lower (safer) doses of chemotherapy drugs to be employed without compromising anti-tumor responses." (PMID 27129149, 2016).
infection (9,231 papers, 1993 to 2026). The state of being infected such as from the introduction of a foreign agent such as serum, vaccine, antigenic substance or organism. "The results showed that infection with the Guizhou strain caused more severe clinical symptoms and intestinal lesions in chickens, accompanied by stronger interleukin (IL)-17 and tumor necrosis factor (TNF)-α responses." (PMID 42050698, 2026). "In vivo, ZDHHC3 mRNA is upregulated in splenic macrophages during infection, and 2-bromopalmitate (2BP) treatment reduces bacterial burden in mice, associated with elevated TNF-α and IFN-γ." (PMID 41486271, 2026). "Transcriptomic data suggest that the infection of T. gondii induced differential gene expression in pathways associated with TNF signaling and cytokine-cytokine receptor interaction." (PMID 40663568, 2025). "During invasion, the host attempts to stop the infection by releasing pro-inflammatory cytokines such as IL-1, IL-6, and Tumor Necrosis Factor-alpha (NTF-ɑ), which causes vasodilation." (PMID 40851808, 2025). "In contrast, the AHI-24 group exhibited upregulation of inflammatory markers such as TNF-α and pro-IL-1β, reflecting general inflammation associated with recent infection." (PMID 41206241, 2025). "The decision to initiate TNF-α inhibitors postoperatively must be carefully weighed against the individual’s infection risk, wound healing status, and the presence of any ongoing infection." (PMID 41465957, 2025). "Infiltrating immune cells following an infection are activated by inflammatory cytokines such as IL-1, IL-6, and TNF-α, which are implicated in RMSF pathology." (PMID 41159782, 2025). "For instance, the high risk of serious infection (including TB reactivation) associated with TNF inhibitors necessitates mandatory pre-screening in clinical practice before the drug can be safely initiated." (PMID 41357870, 2025). "Drug-associated infections and infestations associated with TNF-α inhibitors (adalimumab, infliximab, etanercept, golimumab, and certolizumab pegol) were evaluated using a disproportionality analysis." (PMID 40371340, 2025). "Supernatants were collected 24 hrs after infection and levels of four pro-inflammatory cytokines (TNF-α, IL-1β, IL-8, and IL-6) associated with infection were assessed." (PMID 41550953, 2025). "Mycoplasma-induced necroptosis is caused by autocrine TNF-α during infection which is consistent with the upregulation of plasma TNF-α concentrations that were observed here." (PMID 40121482, 2025). "The difference in infection risk for TNF-α inhibitors to be mostly explained by their different molecular structures, leading to differences in pharmacokinetics and mechanisms of action." (PMID 40371340, 2025). "In contrast to our expectation, we found that infection of T24/83 cells with the tcpC-deficient CFT073ΔtcpC strain resulted in statistically significant lower amounts of IL-6 and TNFα." (PMID 41310197, 2025). "Tumor Necrosis Factor Alpha (TNFα) is a cytokine released during the inflammation caused by infections." (PMID 41003928, 2025). "A particularly elevated risk of developing severe infections is associated with the administration of anti-tumor necrosis factor (TNF) therapy." (PMID 40573926, 2025). "In the PKR-deficient control cells, MYXV∆029L∆156R infection led to a strong induction of TNFα and IL-6 expression." (PMID 40872887, 2025). "Activated pathways in the 3dHSC-sEV-treated KCs were strongly associated with TNF signaling and infection response, whereas inhibited pathways were linked to TH2 differentiation, which promotes M2 macrophage polarization." (PMID 40211350, 2025). "This study identified that the use of TNF-α inhibitors increased the infection risk in older adults." (PMID 40371340, 2025). "This Breg expansion is associated with reduced IFNγ/IL10 ratio, reduced TNFα production and impaired activation of myeloid cells, likely compromising the innate response to infection." (PMID 41191641, 2025).
infection (continued). "The same work described that BALB/c mice exposed to a low dose of LPS prior to IAV H1N1 (A/Fort Monmouth/1/1947) infection exhibited reduced weight loss, lung injuries, and respiratory levels of TNF-α, IL-6, and IL-18." (PMID 40565228, 2025). "FluA infection triggers an excessive release of proinflammatory cytokines (e.g., IL-6, TNF-α, and IFN-γ), leading to a “cytokine storm,” a hallmark of systemic inflammation." (PMID 41321454, 2025). "The analysis of the surviving rainbow trout after the bath challenges indicated that genes associated with immune markers, such as CD4, IL-1β, IL-10 and TNF-α, showed minimal response (in gene regulation) to infections caused by P. salmonis." (PMID 41334221, 2025). "This study is comparable to another review of the German Biologics Register which found that there is a higher relative risk of infection with tocilizumab use as compared to those being treated with anti-TNF therapy." (PMID 40236366, 2025). "Specifically, an increase in inflammatory cytokines such as IL-6, IL-17 A and TNF-α has been observed in wound fluids during infections, especially those associated with biofilm-forming bacteria." (PMID 40873569, 2025). "IPA analyses of differentially expressed genes in 3dHSC-sEVs treated KCs revealed that the activated pathways were strongly associated with TNF signaling and infection response." (PMID 40211350, 2025). "Separating individuals with TBI based on time since likely Mtb exposure revealed that more recent infection was associated with reduced IFNγ responses and a higher proportion of IL-2/TNF-secreting cells." (PMID 41159744, 2025). "Consistent with prior reports, nutritional intervention significantly improved short-term nutritional and immune indicators (PA, Hb, TLC, IgA, IgG, IgM) and reduced inflammatory cytokines (IL-2, IL-6, TNF-α), thereby lowering infection risk." (PMID 41306668, 2025). "Some adult studies have reported that patients treated with anti-TNF therapy are at greater risk of breakthrough infection than patients treated with vedolizumab." (PMID 40573880, 2025). "In order to evaluate the infection risk of TNF-α inhibitors from a large sample viewpoint, we conducted a real-world retrospective and pharmacovigilance analysis utilizing FARES database." (PMID 40371340, 2025). "In particular, identifying polyfunctional CD4+ T cell subsets co-expressing IFN-γ and TNF-α offers promising biomarker candidates to enhance diagnostic specificity, especially for distinguishing between exposure and active infection stages." (PMID 40990013, 2025). "Myd88-deficiency attenuated secretion of IL-6 and TNFα upon infection with CFT073, while tlr4-deficiency almost completely abolished secretion of both cytokines." (PMID 41310197, 2025). "Through an RNA‐sequencing‐based approach, we observed that copper‐administration or depletion of its transporter CTR1 closely associated with infection and inflammation, including the positive regulation of NF‐κB and TNFα pathways." (PMID 40999870, 2025). "Although overall adverse effects were not significantly increased with the use of biological agents, TNF inhibitors were linked to a higher infection rate." (PMID 40546904, 2025). "While TNF KO mice are susceptible to Mab infection, the contribution of innate cells and adaptive cells to TNF production remains to be dissected." (PMID 40415550, 2025). "TNF cytokine is one of the cytokines that are closely associated with Mtb and are essential for controlling infection." (PMID 40396746, 2025). "Although infection is an established risk of immunomodulators and anti-TNFα drugs in the general population, the included studies reported mixed results in those with PSC-IBD." (PMID 41141435, 2025). "Activates macrophages; IFNγR1 deficiency increases infection risk in mice; enhances IL-6, TNF-α production." (PMID 41268545, 2025).